MIR4275 (microRNA 4275)
Synonyms: hsa-mir-4275
Gene: MicroRNA gene on chromosome 4 (28,819,582 to 28,819,668, forward strand). Ensembl gene ENSG00000283275.
Homologues: Orthologues: chimpanzee MIR4275 (100% identical).
Diseases named in the same sentence as MIR4275 in open-access papers:
MIR4275 is named in the same sentence as 1 disease in open-access papers, as found by Europe PMC text mining. Sharing a sentence is not in itself a finding about the gene and the disease. The quoted sentences say what the papers report.
Corneal astigmatism (1 paper, 2025). "In our study, MIR4275 rs292034 was associated with both spherical power and corneal astigmatism, suggesting shared genetic factors." (PMID 40410244, 2025).